MBNL1 (muscleblind like splicing regulator 1)
Diseases named in the same sentence as MBNL1 in open-access papers (continued):
Sharing a sentence is not in itself a finding about the gene and the disease.
retinal degeneration (1 paper, 2017). Degeneration of the retina. "Functional complementation by overexpression of human MBNL1 protein in GMR>DM2-106 rescued the retinal degeneration." (PMID 28623239, 2017).
sarcoma (1 paper, 2025). A usually aggressive malignant neoplasm of the soft tissue or bone. "Also, in SCA7 models, the RBPs TDP-43, Muscleblind-like splicing regulator 1 (MBNL1), and fused in sarcoma (FUS) are recruited to expanded ATXN7 aggregates." (PMID 41213927, 2025).
Spinocerebellar ataxia type 3 (1 paper, 2019). "Rather, our findings in FUS-linked ALS are consistent with previous work performed in a Drosophila model for spinocerebellar ataxia type 3, in which overexpression of MBNL1-enhanced ataxin-3 induced neurodegeneration." (PMID 31811140, 2019).
stomach adenocarcinomas (1 paper, 2022). "MBNL1 was found to be downregulated in various common cancers, such as breast, lung, and stomach adenocarcinomas, and downregulation of MBNL1 predicted poor overall survival in patients with these cancers." (PMID 36217202, 2022).
cancer (30 papers, 2012 to 2025). A tumor composed of atypical neoplastic, often pleomorphic cells that invade other tissues. "Previous studies showed the RNA substrate-dependent splicing activity of MBNL1 isoforms differing in e7 encoded amino-acid tract in normal and cancer cells." (PMID 37882878, 2023). "For instance, increased production of DDX5 and DDX17 has been linked to tumorigenesis in certain types of cancer, while MBNL1 isoforms have been found to differently affect cancer cell viability and migration." (PMID 37882878, 2023). "We suggest that the STAT3/miR-130b-3p/MBNL1 feedback loop is critical for mTORC1-mediated angiogenesis and tumor growth, and that it can be targeted for the treatment of cancers associated with dysregulated mTORC1 activity." (PMID 36217202, 2022). "MBNL1 and MAP2K7Δexon2 promote cancer stemness and increased susceptibility to JNK inhibition." (PMID 39717752, 2024). "Moreover, MBNL1 has been implicated in other neuromuscular disorders and cancers." (PMID 40565550, 2025). "This analysis predicts that MBNL1 has a profound effect on anti-tumor T cell infiltration, similar to that of genes with explicit roles in T cell-mediated killing of cancer cells." (PMID 40305509, 2025). "Strikingly, MBNL1 showed a significant positive correlation for T cell infiltration (based on CD8A expression) for 27 of 29 analyzed TCGA cancer types." (PMID 40305509, 2025). "While the overall expression of MBNL1 was downregulated, exon 7 in the MBNL1 transcript was the most differentially included exon in several cancers including PC, and was essential for the homodimerization of the MBNL1 protein." (PMID 40302801, 2025). "MBNL1 regulates alternative splicing and can be up- or downregulated depending on the type of cancer." (PMID 38720891, 2024). "We propose that elevated miR-130b-3p resulting from hyperactivated mTORC1 signaling inhibits MBNL1 expression and then facilitates tumor angiogenesis and progression in some mTORC1-related cancers." (PMID 36217202, 2022). "Taken together, these data revealed that the mTORC1/STAT3/miR-130b-3p/MBNL1 signaling cascade is also present in human cancer cells." (PMID 36217202, 2022). "The overexpression of MBNL1 was observed in our present dataset, in accordance with the emerging positive regulation of MBNL1 by CREB1 in cancer." (PMID 35421923, 2022). "MBNL1 is downregulated in several common cancers, low MBNL1 is correlated with poor overall survival and increased relapse and distant metastasis." (PMID 34659561, 2021). "By doing so, we discovered that whereas MBNL1 levels are overall down-regulated between normal and cancer tissues, MBNL1 exon 7 (ex7) inclusion increases in almost all tumor samples." (PMID 30456384, 2018). "We identified exon 7 (ex7) in the MBNL1 (Muscleblind-like 1) transcript as being the most differentially included exon in cancer, both in cell lines and in patients' samples." (PMID 30456384, 2018). "Strikingly, MBNL1 ex7 was among the highest included exons between normal and cancer tissues in all analyzed datasets." (PMID 30456384, 2018). "Following these observations, we expanded our analysis to assess the level of MBNL1 ex7 inclusion in other cancer types." (PMID 30456384, 2018). "Furthermore, MBNL1 has been reported to play roles in the inhibition of glioblastoma tumor initiation and suppression of metastasis in breast and colon cancers." (PMID 40305509, 2025). "However, we did not dig into the molecular mechanism by which tRF‐1‐Ser affects MBNL1 nuclear transport because there is currently limited research on protein interactions related to MBNL1 nuclear transport in cancer." (PMID 38725048, 2024). "The isoforms of the MBNL1 protein affect cancer development and are targets for drug development." (PMID 33841514, 2021).
cancer (continued). "Our data demonstrate the importance of studying gene function at the level of alternative spliced isoforms and support our conclusion that MBNL1 Δex7 proteins are antisurvival factors with a defined tumor suppressive role that cancer cells tend to down-regulate in favor of MBNL +ex7 isoforms." (PMID 30456384, 2018). "Extending our analysis to matched patients' tissues from the TCGA PRAD dataset, MBNL1 ex7 was found to be consistently more included in cancer compared to normal prostate tissue, whereas the decrease in overall mRNA transcripts is consistent for most of the patients." (PMID 30456384, 2018). "In detail, MBNL1 could suppress cancer metastasis via binding to the 3′ untranslated regions (UTRs) of DBNL in breast and contribute to the carcinogenesis in the form of miRNA-MBNL1 in colorectum." (PMID 29383134, 2017). "Indeed, depletion of MBNL1 significantly accelerated cell proliferation, suggesting that the MBNL1/PD-1 axis could potentially modulate cancer cell proliferation but more direct evidence is required." (PMID 37202440, 2023). "Extending our analysis to human cancers, we found that MBNL1 expression positively correlates with CD8A expression and cytolytic T cell activity, suggesting a conserved role for MBNL proteins in regulating T cell infiltration and function." (PMID 40305509, 2025). "Taken together, these data indicate that Mbnl1 and, to a lesser degree, Mbnl2, have direct roles in modulating MHC Class I-dependent killing of cancer cells by antigen-specific T cells." (PMID 40305509, 2025). "For example, Mbnl1 is reported to play a role in stabilizing metastatic suppressors such as Snail, DBNL, and TACC1, thereby preventing cancer metastasis." (PMID 39996710, 2025). "The human homologs of the top three RNA binding proteins identified in our screen, MBNL2, MBNL1 and RBFOX2, are differentially regulated in cancer transcriptionally and post-transcriptionally through alternative splicing." (PMID 38114498, 2023). "Additionally, our data link the RNA binding proteins CUG-BP1 and MBNL1 with IR alternative splicing and this interplay between the two could further be exploited in therapeutic and mechanistic directions for other cancers and diseases for which insulin signaling is affected." (PMID 35017650, 2022). "Five of these 25 alternatively spliced genes are well-known to play a role in cancer (ARHGEF11, CD44, CTNND1, ENAH, MBNL1)." (PMID 33845831, 2021). "According to the results of the analysis of malignant tumors, NCOA1, HERC1, HIPK3, MBNL1, hsa-let-7b-3p, hsa-miR-378a-5p, and hsa-miR-26a-5p were predictive or prognostic factors for malignant tumors." (PMID 33841514, 2021). "Specific splicing regulators, including RBFOX2, MBNL1/2 and QKI, appear to account for many splicing alteration events in multiple cancer types." (PMID 25908786, 2015). "We show that many of these events are shared among different cancer types; our data also suggest that specific splicing factors, namely RBFOX2, QKI, MBNL1/2, PTBP1 and CELF2 are probably responsible for many of the alterations detected in these cancer types." (PMID 25908786, 2015). "Opposite trends of expression changes were observed for QKI, MBNL1 and CELF2 in the KIRC compared to other cancer types (upregulation in KIRC versus downregulation in other cancer type)." (PMID 25908786, 2015). "We screened publicly available data to find that CRISPR knockout of MBNL1 does not directly affect cancer cell viability." (PMID 40305509, 2025). "Thus, the combination of Mbnl1 and Mbnl2 DKO is likely more deleterious to cancer cell growth than the knockout of either gene alone, again highlighting the likely functional redundancy of these proteins." (PMID 40305509, 2025). "We report that whereas the absence of MBNL1 is tolerated in cancer cells, the expression of isoforms lacking ex7 (MBNL1 Δex7) induces DNA damage and inhibits cell viability and migration, acting as dominant negative proteins." (PMID 30456384, 2018).
cancer (continued). "MBNL1 proteins lacking exon 7 (−ex7) are antisurvival factors with tumor suppressive role that cancer cells tend to down-regulate in favor of MBNL +ex7 isoforms." (PMID 30456384, 2018). "The general aims of our study were to determine the phenotypical implications of the presence/absence of MBNL1 ex7 in cancer, while understanding its upstream regulators and downstream molecular mechanisms of action." (PMID 30456384, 2018). "MBNL1/2, RBFOX2 and QKI were downregulated in most of the cancer types and, as expected, their motifs were enriched in these cancer types upstream to exons with higher exclusion and downstream to exons with higher inclusion in cancer." (PMID 25908786, 2015). "This opposite splicing regulation in KIRC, may result –in part- from the opposite change in level of expression of QKI, MBNL1 and CELF2 that we detected in KIRC compared to other cancer types." (PMID 25908786, 2015). "MBNL1 was not regulated by CREB1 in normal, while positively regulated by CREB1 in cancer." (PMID 35421923, 2022).
tumor (18 papers, 2018 to 2025). "MBNL1 depletion rescued the compromised angiogenesis and tumor growth caused by miR-130b-3p inhibition." (PMID 36217202, 2022). "MBNL1, a tissue-specific RNA metabolism regulator, was an important regulator of tumor metastasis and growth." (PMID 37189064, 2023). "We demonstrate that aberrantly activated mTORC1 contributes to angiogenesis and tumor growth by regulating of the STAT3/miR-130b-3p/MBNL1 feedback loop." (PMID 36217202, 2022). "IHC study showed that the expression of MBNL1 was positively correlated with CREB1 in tumor samples (n = 56, r = 0.419, P = 0.01), and the correlation between CREB1 and MBNL1 was insignificant in normal gastric samples (n = 52, r = 0.153, P = 0.276)." (PMID 35421923, 2022). "The STAT3/miR-130b-3p/MBNL1 feedback loop plays a vital role in mTORC1-mediated angiogenesis and tumor progression." (PMID 36217202, 2022). "The mediation effect of MBNL1 on the miR-130b-3p-regulated angiogenesis and tumor growth was further confirmed using a subcutaneous xenograft tumor model." (PMID 36217202, 2022). "Decreased p-STAT3 expression was observed in tumor tissues derived from MBNL1-overexpressing NTC/T2 null cells compared with the control cells." (PMID 36217202, 2022). "Taken together, these data revealed that miR-130b-3p promotes angiogenesis and tumor growth at least partially through suppression of MBNL1 expression." (PMID 36217202, 2022). "MBNL1 also inhibits tumor cell metastasis through regulating the stability of Snail, TACC1 and DBNL 28,29." (PMID 34659561, 2021). "Other examples of downregulated SF genes are the muscleblind-like 1 (MBNL1) gene that acts as a tumor suppressor in BC by controlling AS, translation, and RNA decay through binding at 3′UTRs." (PMID 34944881, 2021). "In contrast, MBNL1 overall expression was down-regulated, consistently with its described role as a tumor suppressor." (PMID 30456384, 2018). "MBNL1 participated in the regulation of alternative RNA splicing in tumor growth and metastasis." (PMID 38890701, 2024). "Moreover, decreased p-STAT3 expression in tumor tissues derived from anti-miR-130b-3p-expressing NTC/T2 null was partially rescued by knockdown of MBNL1." (PMID 36217202, 2022). "The in vivo function of MBNL1 was further evaluated using a subcutaneous xenograft tumor model." (PMID 36217202, 2022). "Furthermore, we confirmed that elevated miR-130b-3p driven by aberrantly activated mTORC1 signaling promotes angiogenesis and tumor growth through downregulation of MBNL1." (PMID 36217202, 2022). "MBNL1 inhibits tumor metastasis by modulating the stability of DBNL, TACC1, and Snail mRNA." (PMID 33466733, 2021). "Noteworthy, MBNL1 was highly expressed in both tumor and stroma cells, while NOVA1 and RBMS3 were dominantly expressed in tumor stroma." (PMID 39980011, 2025). "The study revealed that MBNL1 was downregulated in GBM tissues and cells, and functioned as tumor suppressor." (PMID 36463205, 2022). "To confirm the roles of BUD13, CDK12, and MBNL1 in tumor growth in vivo, we subcutaneously injected GBM BUD13(-) cells, CDK12(-) cells, MBNL1(+) cells, or a combination of the three cells to construct nude mice xenograft models." (PMID 36463205, 2022). "Collectively, our results indicate that MBNL1 and circNTRK2 inhibit the glycolysis and proliferation of GBM cells, thereby functioning as tumor suppressors." (PMID 36064939, 2022). "Our findings help in the elucidation of the molecular mechanism by which dysregulated mTORC1 signaling drives tumor angiogenesis, indicating that the components in the STAT3/miR-130b-3p/MBNL1 loop signaling pathway may be targeted for the treatment of mTORC1-related tumors." (PMID 36217202, 2022).
myopathy (6 papers, 2015 to 2024). A disease of the muscle in which the muscle fibers do not function properly. "Thus, even with combined MBNL1 loss and partial MBNL2 depletion, there was upregulation of MuSCs in response to myopathy but limited dystrophic changes." (PMID 38473933, 2024). "Given the myopathic changes in Mbnl1−/−/Mbnl2+/− mice, and the lack of significant myopathy or changes in Pax7 expression and MuSCs in the individual knockout lines, we decided to evaluate the Mbnl1−/−/Mbnl2+/− mice for these parameters." (PMID 38473933, 2024).
neuromuscular disease (4 papers, 2013 to 2025). "For example, Mbnl1 and Mbnl2 sequestration is known to contribute significantly to cellular dysfunction via RNA misprocessing in neuromuscular disease." (PMID 40305509, 2025).
cardiovascular diseases (3 papers, 2012 to 2023). "At 4 weeks post-MI, 4 genes (DOCK9, MBNL1, RRAD, and ZSWIM6) by all of 37 unique altered transcripts were related to cardiovascular disease." (PMID 23372767, 2013). "We found that four of the predicted disease genes, namely, ATF4, MBNL1, NCKAP1 and CXCL14, have been reported to be related to cardiovascular diseases." (PMID 22923290, 2012).
heart disease (3 papers, 2010 to 2024). "Many of these MBNL1-dependent splice variants, along with MBNL1 itself, have also been implicated in the disease progression of myotonic dystrophy type I (DM1), for which heart disease and sudden cardiac death are prominent causes of mortality." (PMID 38818408, 2024). "As alterations in MBNL1 and CUG-BP1 levels or function can result in splice errors, cardiac dysfunction and death, it will be particularly important to understand the molecular events that regulate the activity of this pair of proteins in heart disease." (PMID 25761764, 2015).
infection (2 papers, 2015 to 2024). The state of being infected such as from the introduction of a foreign agent such as serum, vaccine, antigenic substance or organism. "In cultured dermal fibroblasts isolated from conditional MBNL1 TGs, we observed that this LoxP-dependent MBNL1 transgene was effectively induced after adenoviral Cre (AdCre) infection." (PMID 26670661, 2015). "Mbnl1−/− MEFs are refractory to TGFβ-induced myofibroblast differentiation, but this defect was rescued to wild-type levels by Adenovirus encoding SRF (AdSRF) infection." (PMID 26670661, 2015).
neurological diseases (2 papers, 2019 to 2020). "Mbnl1, an important neural development splicing factor widely studied for its implications in neurological disorders, was unequivocally identified as AltTEM-regulated (DIU FDR = 0.0018, total change = 23.51, positive for isoform switching)." (PMID 32423416, 2020).
neurodegenerative disease (1 paper, 2019). A disorder of the central nervous system characterized by gradual and progressive loss of neural tissue and neurologic function. "MBNL1 has been linked to numerous neurodegenerative diseases and is best known for its involvement in myotonic dystrophy." (PMID 31811140, 2019).
MBNL1 also shares sentences with these, for which no sentence is quoted: glioblastoma (5 papers); Fuchs endothelial corneal dystrophy (3); Arrhythmia (2); autism (2); genetic diseases (2); laryngeal squamous cell carcinoma (2); limb-girdle muscular dystrophy (2); Myocardial fibrosis (2); Ventricular hypertrophy (2); amyloid (1); Angiofibroma (1); autosomal dominant disease (1); Becker muscular dystrophy (1); colon cancer (1); coronary atherosclerosis (1); cutaneous squamous cell carcinoma (1); depression (1); diabetic cardiomyopathy (1); distal myopathy (1); Emery-Dreifuss muscular dystrophy (1); esophageal cancer (1); facioscapulohumeral muscular dystrophy (1); fibrosis (1); follicular lymphoma (1); Glucose intolerance (1); Intellectual disability (1); left ventricular noncompaction (1); leiomyosarcoma (1); malignant glioma (1); mitral valve prolapse (1).
A further 7 diseases each share a sentence with MBNL1 in 1 paper.